ZNF676 (zinc finger protein 676)
Description:
May be involved in transcriptional regulation.
Tractability: PROTAC: ubiquitination databases record sites on it.
Gene: Protein-coding gene on chromosome 19 (22,178,486 to 22,215,801, reverse strand). Ensembl gene ENSG00000196109.
Subcellular location: Nucleus
Pathways (Reactome):
Gene expression (Transcription): Generic Transcription Pathway
Gene Ontology:
Molecular function: DNA-binding transcription factor activity, RNA polymerase II-specific; RNA polymerase II cis-regulatory region sequence-specific DNA binding
Biological process: regulation of DNA-templated transcription; regulation of transcription by RNA polymerase II
Cellular component: nucleus
Genetic constraint (gnomAD): Loss-of-function variants: 5 observed, 5.28 expected, observed/expected ratio (o/e) 0.95, 90% interval 0.49 to 1.77. That is too few expected variants to judge how well the gene tolerates losing a copy. Missense variants: 632 observed, 626.9 expected, observed/expected ratio (o/e) 1.01, 90% interval 0.94 to 1.08. Synonymous variants: 194 observed, 198.56 expected, observed/expected ratio (o/e) 0.98, 90% interval 0.87 to 1.1.
Homologues: Orthologues: chimpanzee ZNF676 (99% identical). Paralogues in human: ZNF728 (80% identical), ZNF726 (71% identical), ZNF254 (71% identical), ZNF724 (66% identical), ZNF85 (65% identical), ZNF708 (64% identical), ZNF43 (63% identical), ZNF90 (62% identical), ZNF492 (62% identical), ZNF93 (62% identical), ZNF429 (61% identical), ZNF681 (61% identical), and 164 more.
Diseases named in the same sentence as ZNF676 in open-access papers:
ZNF676 is named in the same sentence as 7 diseases in open-access papers, as found by Europe PMC text mining. Sharing a sentence is not in itself a finding about the gene and the disease. The quoted sentences say what the papers report.
Azoospermia (2 papers, 2021 to 2022). Absence of any measurable level of sperm,whereby spermatozoa cannot be observed even after centrifugation of the semen pellet. "The authors also observed that ZNF676 is co-expressed with the ZNF678 gene, where lies a risk locus for azoospermia." (PMID 33921254, 2021). "The ZNF676 gene was reported as a risk locus in nonobstructive azoospermia by means of a Transcriptome-wide association study (TWAS) in a Chinese population." (PMID 33921254, 2021).
breast carcinoma (1 paper, 2023). "The gene with the highest MS was ZNF676, which is closely associated with the PRMT1 gene that is involved in breast cancer metastasis." (PMID 37761960, 2023).
myopia (1 paper, 2024). "In contrast, in our study, we found that each rare T allele of the ZNF676 rs412658 polymorphism was associated with 4-fold decreased odds of a high myopia degree occurrence (OR = 0.269; 95% CI: 0.090–0.807; p = 0.019)." (PMID 38540151, 2024). "The evaluation of the genotype distributions of the polymorphisms in the myopia patients showed that ZNF676 rs412658 CT genotype carriers have 4-fold decreased odds of high myopia occurrence (OR = 0.250; CI: 0.076–0.826; p = 0.023)." (PMID 38540151, 2024). "Also, the evaluation of the allele distributions of the polymorphisms in the myopia group showed that the ZNF676 rs412658 T allele was associated with similarly decreased odds of high myopia (OR = 0.269; 95% CI: 0.090–0.807; p = 0.019)." (PMID 38540151, 2024). "Also, the evaluation of the allele distributions of the polymorphism under the additive genetic model in the myopia group showed that the ZNF676 rs412658 T allele was associated with similar odds of high myopia (OR = 0.269; 95% CI: 0.090–0.807; p = 0.019)." (PMID 38540151, 2024). "On the other hand, the ZNF676 rs412658 T allele may protect against a high myopia degree occurrence, but further analysis with larger study groups is necessary to confirm these findings." (PMID 38540151, 2024). "The ZNF676 rs412658 T allele may protect against a high myopia occurrence." (PMID 38540151, 2024). "Our study delves into the associations between ZNF676 and CTC1 gene polymorphisms and their impact on the relative leukocyte telomere length (relative LTL) in myopia, as well as its degree." (PMID 38540151, 2024). "So, the aim of our study was to delve into the associations between ZNF676 and CTC1 gene polymorphisms and their impact on the relative LTL in myopia and its degree." (PMID 38540151, 2024). "The genotypes and allele distributions of ZNF676 rs412658 and CTC1 rs3027234 were examined in the myopia group and compared with the control group." (PMID 38540151, 2024). "The myopia group with the ZNF676 rs412658 CC genotype has statistically significantly shorter leukocyte telomeres than the control group with the same genotype (age ≤ 29), and the p-value is 0.011." (PMID 38540151, 2024). "Also, the myopia group with the ZNF676 rs412658 CT and CTC1 rs3027234 CT genotypes have statistically significantly longer leukocyte telomeres than the control group with the same genotypes (age > 29), with p-values that are, respectively, 0.016 and 0.012." (PMID 38540151, 2024). "Similarly, the analysis of the association between the relative LTL and ZNF676 rs412658 and CTC1 rs3027234 genotypes with gender was conducted in the myopia group." (PMID 38540151, 2024). "Also, myopia patients showed that ZNF676 rs412658 CT genotype carriers have 4-fold decreased odds of a high myopia degree occurrence (OR = 0.250; CI: 0.076–0.826; p = 0.023)." (PMID 38540151, 2024). "Therefore, this study aims to investigate the associations between ZNF676 rs412658 and CTC1 rs3027234, along with the measurement of relative leukocyte telomere length (LTL) in relation to the occurrence of myopia and its degree." (PMID 38540151, 2024). "The association of the relative LTL and the ZNF676 rs412658 and CTC1 rs3027234 polymorphisms with the incidence and degree of myopia has not yet been analyzed." (PMID 38540151, 2024).
pituitary adenoma (1 paper, 2024). "TERF1 rs1545827, TNKS2 rs10509637 and rs10509639, TERF2 rs251796, ZNF676 rs412658, and CTC1 rs3027234 genes’ single nucleotide polymorphisms were analyzed to evaluate the associations with pituitary adenoma relapse." (PMID 38339395, 2024).
soft tissue sarcoma (1 paper, 2024). A malignant neoplasm arising from muscle tissue, adipose tissue, blood vessels, fibrous tissue, or other supportive tissues excluding the bones. "Analyzing the interactions of ZNF676 rs412658, Xu and co-researchers found that the influence of the ZNF676 rs412658 polymorphism was associated with soft tissue sarcoma (SAC) and LTL." (PMID 38540151, 2024).
ZNF676 also shares sentences with these, for which no sentence is quoted: cancer (1 paper); tumor (1).